CD2AP (CD2 associated protein)
Description:
Seems to act as an adapter protein between membrane proteins and the actin cytoskeleton. In collaboration with CBLC, modulates the rate of RET turnover and may act as regulatory checkpoint that limits the potency of GDNF on neuronal survival. Controls CBLC function, converting it from an inhibitor to a promoter of RET degradation (By similarity). May play a role in receptor clustering and cytoskeletal polarity in the junction between T-cell and antigen-presenting cell (By similarity). May anchor the podocyte slit diaphragm to the actin cytoskeleton in renal glomerolus. Also required for cytokinesis. Plays a role in epithelial cell junctions formation.
Synonyms: CMS
Tractability: Antibody: its Gene Ontology location is reachable by antibodies, with high confidence; the Human Protein Atlas places it where antibodies can reach. PROTAC: UniProt records ubiquitination sites on it; ubiquitination databases record sites on it; its protein half-life has been measured.
Gene: Protein-coding gene on chromosome 6 (47,477,752 to 47,627,263, forward strand). Ensembl gene ENSG00000198087.
Subcellular location: Cytoplasm, cytoskeleton; Cell projection, ruffle; Cell junction
Subcellular location (Human Protein Atlas): Plasma membrane; Centriolar satellite
Pathways (Reactome):
Cell-Cell communication: Nephrin family interactions
Gene Ontology:
Molecular function: cadherin binding; identical protein binding; protein binding; SH3 domain binding; protein-macromolecule adaptor activity; structural constituent of cytoskeleton; actin binding; actin filament binding; clathrin binding; phosphatidylinositol 3-kinase regulatory subunit binding
Biological process: actin filament organization; negative regulation of small GTPase mediated signal transduction; positive regulation of protein secretion; cell migration; protein-containing complex assembly; signal transduction; substrate-dependent cell migration, cell extension; synapse organization
Cellular component: anchoring junction; extracellular exosome; filamentous actin; plasma membrane; ruffle; actin cytoskeleton; axon; cell leading edge; cytoplasm; dendrite; vesicle; actin filament; cell periphery; cell-cell junction; cytoskeleton; growth cone; late endosome; neuromuscular junction; neuron projection; nuclear envelope lumen; podosome; protein-containing complex; slit diaphragm; trans-Golgi network membrane
Genetic constraint (gnomAD): Loss-of-function variants: 28 observed, 47.13 expected, observed/expected ratio (o/e) 0.59, 90% interval 0.44 to 0.81. The upper end of that interval is the gene's LOEUF score, 0.81, which puts it in group 3 of 6, group 1 being the genes least tolerant of losing a copy. Missense variants: 486 observed, 475.93 expected, observed/expected ratio (o/e) 1.02, 90% interval 0.95 to 1.1. Synonymous variants: 165 observed, 171.24 expected, observed/expected ratio (o/e) 0.96, 90% interval 0.85 to 1.1.
Gene-disease validity (ClinGen):
ClinGen rates the evidence that CD2AP causes each of these diseases.
focal segmental glomerulosclerosis 3, susceptibility to (autosomal recessive): Definitive.
inherited focal segmental glomerulosclerosis (autosomal dominant): Moderate. An instance of focal segmental glomerulosclerosis that is caused by an inherited genomic modification in an individual.
Homologues: Orthologues: chimpanzee CD2AP (99% identical), macaque CD2AP (96% identical), dog CD2AP (91% identical), pig CD2AP (89% identical), mouse Cd2ap (86% identical), rat Cd2ap (84% identical), guinea pig CD2AP (83% identical), tropical clawed frog cd2ap (55% identical), zebrafish cd2ap (51% identical), Drosophila melanogaster cindr (24% identical), Caenorhabditis elegans cdap-2 (17% identical). Paralogues in human: SH3KBP1 (39% identical), MNMIP1 (24% identical), NOSTRIN (10% identical).
Diseases named in the same sentence as CD2AP in open-access papers:
CD2AP is named in the same sentence as 81 diseases in open-access papers, as found by Europe PMC text mining. Sharing a sentence is not in itself a finding about the gene and the disease. The quoted sentences say what the papers report.
Alzheimer disease (31 papers, 2011 to 2025). A progressive, neurodegenerative disease characterized by loss of function and death of nerve cells in several areas of the brain leading to loss of cognitive function such as memory and language. "Polymorphisms in the gene encoding CD2-associated protein (CD2AP) are associated with an increased risk for developing Alzheimer’s disease (AD)." (PMID 40462155, 2025). "The CD2AP gene is also linked to left angular gyrus CBF in the Alzheimer's Disease Neuroimaging Initiative cohort." (PMID 40462155, 2025). "The initial interest in brain CD2AP was sparked by the identification of genetic variants in the non-coding and coding regions of CD2AP in patients with Alzheimer’s disease (AD) via Genome-Wide Association Studies (GWAS)." (PMID 40462155, 2025). "Single nucleotide polymorphisms (SNPs) in the CD2AP gene have been associated with Alzheimer’s disease (AD)." (PMID 39695808, 2024). "Since 2011, three large-scale genome-wide association studies (GWAS) have confirmed that the CD2AP rs9349407 polymorphism is significantly connected with Alzheimer’s disease (AD) in individuals of European descent." (PMID 36338943, 2022). "Recently, CD2AP was identified as a genetic risk factor for Alzheimer’s disease (AD) by several genome-wide association studies." (PMID 25887956, 2015). "Common variations of CD2AP have been associated with kidney problems and late-onset Alzheimer’s diseases, in which CD2AP was found to be involved in the abnormal cytoskeletal structural regulation and cell–cell contacts." (PMID 24776925, 2014). "Interestingly, CD2AP is an Alzheimer's disease (AD) risk gene upregulated in the microglia of individuals with AD, which are implicated in phagocytic responses to amyloid-β." (PMID 41208482, 2025). "Furthermore, two additional studies including patients from the Religious Order Study (ROS), the Rush Memory and Aging Project and the Alzheimer’s Disease Neuroimaging Initiative confirm that CD2AP SNPs rs9381563 and rs10948363 are linked to higher CSF ptau and neurofibrillary tangles." (PMID 40462155, 2025). "In fact, variants at numerous other genetic loci related to endocytic trafficking and synaptic maintenance have been discovered as risk factors for Alzheimer’s disease (BIN1, PICALM, CD2AP, SORL1) and Parkinson’s disease (SNCA, LRRK2, SH3GL2/EndoA, RAB7L1)." (PMID 32286230, 2020). "In this review we discuss our current knowledge of the risk genes APOE4, BIN1, CD2AP, PICALM, PLD3 and TREM2 and their impact on endolysosomal (dys)regulations in the light of late-onset Alzheimer’s disease pathology." (PMID 31159836, 2019). "Genetic variants in PICALM, BIN1, CD2AP, and RIN3 are associated with increased risk of Alzheimer’s disease, all dementia, and suggested vascular dementia independent of the strong APOE ε4 allele." (PMID 30830563, 2019). "We genotyped four variants in PICALM, BIN1, CD2AP, and RIN3 previously identified as top hits for Alzheimer’s disease, in two prospective studies of the general population totaling 74,754 individuals." (PMID 30830563, 2019). "The CD2-associated protein, CD2AP, which also binds to VEEV nsP3 HVD, has been identified as a genetic risk factor for Alzheimer’s disease." (PMID 27509095, 2016). "Mutations or haploinsufficiency of CD2AP have been linked to FSGS and Alzheimer’s disease (AD)." (PMID 41368354, 2025). "Most studies on CD2AP have focused on kidney and Alzheimer’s diseases." (PMID 36359915, 2022).
glomerulosclerosis (14 papers, 2012 to 2025). A hardening of the kidney glomerulus caused by scarring of the blood vessels. "Mice with homozygous mutation of Cd2ap develop severe nephrotic syndrome, with mesangial cell proliferation, extracellular matrix deposition, glomerulosclerosis, extensive foot process effacement and die within weeks of birth." (PMID 25968128, 2015). "Podocyte apoptosis has been proposed as a mechanism of podocyte loss and glomerulosclerosis in a transforming growth factor -β1 transgenic mouse model, a knockout for CD2AP, a puromycin-induced lesion model, and mouse and human glomerular epithelial cell cultures." (PMID 33147279, 2020). "CD2AP-deficient mice develop nephritic syndrome and renal failure caused by glomerulosclerosis." (PMID 22880102, 2012). "The Cd2ap mutant mouse is therefore an excellent model system for the study of podocyte dysfunction driven glomerulosclerosis." (PMID 25968128, 2015). "Research indicates that urinary release of podocyte-derived exosomal CD2AP mRNA is negatively correlated with the extent of renal fibrosis and glomerulosclerosis, suggesting that CD2AP mRNA could serve as a noninvasive tool to detect renal fibrosis." (PMID 40809416, 2025). "The lack of CD2-associated protein (CD2AP) in mice increases podocyte apoptosis and results in glomerular sclerosis and renal failure." (PMID 30922260, 2019). "CD2AP mRNA correlated negatively with 24 h-urine protein, severity of tubulointerstitial fibrosis and glomerulosclerosis and could discriminate between kidney disease and controls." (PMID 25310591, 2014). "Furthermore, heterozygous CD2AP mice also show proteinuria and glomerulosclerosis-like damage at nine months of age." (PMID 22253810, 2012). "Recently, CD2AP was found to be related to glomerulosclerosis." (PMID 22880102, 2012). "Lack of CD2-associated protein (CD2AP) in mice increases podocyte apoptosis and leads to glomerulosclerosis and renal failure." (PMID 28878342, 2017). "The importance of CD2AP in podocytes is demonstrated by glomerulosclerosis and foot process effacement, leading to renal failure in mice lacking CD2AP." (PMID 28286744, 2017). "Lack of the glomerular expression of CD2AP in animals produces mesangial cell proliferation with extracellular matrix deposition, glomerulosclerosis, and extensive foot-process effacements that are correlated with the entity of the defect." (PMID 22675377, 2012).
nephrotic syndrome (13 papers, 2012 to 2025). A collection of symptoms that include severe edema, proteinuria, and hypoalbuminemia; it is indicative of renal dysfunction. "Genetic variants in NPHS1, NPHS2, and CD2AP demonstrate the strongest causal link to human nephrotic syndromes, reflecting their indispensable structural and signaling functions." (PMID 41368354, 2025). "Homozygous mutations in the CD2AP gene lead to early-onset nephrotic syndrome, characterized by severe proteinuria, podocyte effacement, and rapid progression to end-stage renal disease (ESRD)." (PMID 41368354, 2025). "CD2AP is essential for SD integrity and podocyte permselectivity since CD2AP knockout caused mice to develop nephrotic syndrome." (PMID 34288970, 2021). "CD2AP has a role in glomerular filtration by maintaining podocyte intercellular junctions, and its deficiency leads to albumin excretion and nephrotic syndrome." (PMID 34356879, 2021). "Because Cd2ap mutations have been associated with nephrotic syndrome and FSGS in humans, the results of this study translate to a deeper molecular understanding of this genetic disease." (PMID 25968128, 2015). "Additional variants in endocytosis proteins important for SD maintenance and function have been associated with nephrotic syndrome in patients, including variants in Myosin-1E (Myo1E; binds Dynamin and Synaptojanin), and CD2AP (a major binding partner of Endophilin)." (PMID 35265622, 2022). "Together, nephrin, podocin, and CD2AP form a tripartite mechanosensory complex, and their collective disruption results in congenital or steroid-resistant nephrotic syndromes." (PMID 41368354, 2025). "Yet another factor that is essential to slit diaphragm integrity in both zebrafish and mammals is cd2-associated protein (cd2ap), and animals lacking this protein exhibit podocyte effacement, edema, and the symptoms of the nephrotic syndrome." (PMID 36810461, 2023). "While CD2AP is a disease causing gene for human FSGS, the temporal relationship between albuminuria and morphometric glomerular changes has implications beyond the CD2AP KO experimental model and genetic causes of nephrotic syndrome." (PMID 34568396, 2021). "Indeed, using an established genetic model of nephrotic syndrome (Cd2ap knockout animals) and sheep derived nephrotoxic serum (NTS), we could demonstrate that in both conditions tested, CXADR was strikingly up-regulated." (PMID 26076477, 2015). "Cd2ap gene expression did not change in our study, in contrast to what was shown in other studies of nephrotic syndrome patients." (PMID 26545114, 2015). "Interestingly, mice lacking Cd2ap develop nephrotic syndrome and die at 6–7 weeks of age due to kidney failure." (PMID 35223901, 2022).
renal failure (11 papers, 2012 to 2024). "The lack of appropriate mouse models for evaluating the effects of CD2AP deficiency on learning and memory is a major challenge in the current context, primarily due to premature death from renal failure at 6–7 weeks of age in existing models." (PMID 39696695, 2024). "Studies have been elucidated that CD2AP is silenced in acute renal failure caused via LPS-stimulated sepsis." (PMID 35172672, 2022). "On the other hand, CD2AP-deficient pups show proteinuria from two weeks of age onward, and most die of renal failure at six to seven weeks of age." (PMID 22253810, 2012). "Finally, CD2AP-null mice died at 6–7 weeks of age from renal failure and mutations in the CD2AP gene leading to haplo-insufficiency have been identified in several families with FSGS." (PMID 23176147, 2013). "Consistent with previous studies, global knockout of Cd2ap resulted in low body weight and early death at 6–7 weeks of age due to renal failure." (PMID 39696695, 2024). "We found that tankyrases interact with CD2-associated protein (CD2AP), a protein essential for kidney ultrafiltration as CD2AP-knockout (CD2AP−/−) mice die of kidney failure at the age of 6–7 weeks." (PMID 27441654, 2016). "CD2AP knockout mice were generated and found to develop a rapid onset nephrotic syndrome and renal failure at 3 weeks of age." (PMID 22880102, 2012). "Lack of CD2AP predisposes cells to apoptosis, and therefore reduced level of MMP-9, shown to protect tubular cells against apoptosis in acute kidney injury, could contribute to the susceptibility of CD2AP-deficient podocytes to apoptosis." (PMID 27441654, 2016).
glomerular disease (10 papers, 2010 to 2025). "In certain human glomerulopathies and in a CD2AP-deficiency model, nephrin internalization was also found to be stimulated by ubiquitination." (PMID 23437316, 2013). "Haplo-insufficiency of CD2AP due to heterozygous mutations may confer susceptibility to glomerular disease and integrity, as suggested by experiments in CD2AP heterozygous knockout mice." (PMID 19066979, 2010). "Mouse knockout models demonstrate that deficiencies of either podocyte-specific genes, encoding for podocin, nephrin, and Neph1 or more ubiquitously expressed genes, encoding for α-Actn4, CD2AP and Fyn can result in podocyte dysfunction leading to progressive glomerular disease." (PMID 20877463, 2010). "One case is the mRNA encoding CD2-associated protein (CD2AP), which was detected in urinary EVs coming from healthy individuals and glomerular disease patients." (PMID 34204452, 2021). "The low expression of CD2AP may be involved in the pathogenesis of glomerular diseases characterized by podocyte lesions." (PMID 38774964, 2024). "Furthermore, these authors have highlighted the association between the expression of nephrin, podocin, CD2AP, and SYNPO proteins and the development of glomerular disease." (PMID 30919150, 2019). "Recently, some investigators have reported that the levels of the SD and FP proteins, nephrin, podocin, CD2AP, and SYNPO, decrease in glomerular diseases." (PMID 30919150, 2019). "Furthermore, it has been shown that, as demonstrated for other scaffold proteins such as CD2AP, ZO-1 and NEPHRIN itself, the expression of MAGI2 is reduced in glomerulopathies." (PMID 40563084, 2025). "Due to the fact that CD2AP knockout mice have glomerular disease and do not survive beyond a few months of age until plaque onset in PS1APP mice, we also measured the effects of CD2AP haploinsufficiency on amyloid plaque deposition." (PMID 25887956, 2015).
dementia (9 papers, 2014 to 2025). Loss of intellectual abilities interfering with an individual's social and occupational functions. "Genetic variants in the CD2AP locus are associated with increased CSF tau levels in mild cognitive impairment, decreased cognitive function in middle-aged individuals with a family history of AD, and increased risk of AD, all-cause dementia, and vascular dementia." (PMID 40050982, 2025). "Within the neurodegenerative group, two proteins (VKORC1 and STX1B) were shared between AD and PD, and two other proteins (QPCT and CD2AP) were shared between the clinical diagnosis of AD and AD based on both clinical diagnosis and family history of dementia." (PMID 35882878, 2022). "In a comparative analysis of gene expression in MRI type 2, we found a decrease in the expression of ACOX1, BIN1, CD2AP, CD33, TNFR1, VEGFA, and VEGFC genes in clinically significant CI (MCI and dementia) compared to the control group." (PMID 39125683, 2024). "Also, we aimed to investigate the association of candidate loci with the age at the onset of AD and confirmed that the candidate genes including HLA-DRB1, CD2AP, and PTK2B may contribute to the development of early onset dementia." (PMID 32116649, 2020).
focal segmental glomerulosclerosis (8 papers, 2012 to 2025). A renal disorder characterized by sclerotic lesions in the glomeruli. "Functional genetic studies demonstrated that mutations in the CD2AP gene cause a pattern of kidney injury termed focal segmental glomerulosclerosis." (PMID 40462155, 2025). "Mutations in several genes expressed in podocytes, including Cd2ap, have been associated with focal segmental glomerulosclerosis in humans." (PMID 25968128, 2015). "Mutations in Cd2ap have been associated with focal segmental glomerulosclerosis (FSGS) in humans." (PMID 25968128, 2015). "Mutations in CD2AP may cause focal segmental glomerulosclerosis (FSGS) depending on their severity." (PMID 22844592, 2012).